TUBA1A (tubulin alpha 1a)
Description:
Tubulin is the major constituent of microtubules, a cylinder consisting of laterally associated linear protofilaments composed of alpha- and beta-tubulin heterodimers. Microtubules grow by the addition of GTP-tubulin dimers to the microtubule end, where a stabilizing cap forms. Below the cap, tubulin dimers are in GDP-bound state, owing to GTPase activity of alpha-tubulin.
Synonyms: TUBA3; B-ALPHA-1; FLJ25113; LIS3
Tractability: Small molecule: an approved drug acts on it; a structure with a bound ligand is known; a high-quality ligand is known; it belongs to a druggable protein family. Antibody: its Gene Ontology location is reachable by antibodies, with medium confidence. PROTAC: ubiquitination databases record sites on it; its protein half-life has been measured; a small molecule that binds it is known. Other modalities: an approved drug acts on it.
Target class: Structural protein
Gene: Protein-coding gene on chromosome 12 (49,184,686 to 49,189,324, reverse strand). Ensembl gene ENSG00000167552.
Subcellular location: Cytoplasm, cytoskeleton; Cytoplasm, cytoskeleton, flagellum axoneme
Subcellular location (Human Protein Atlas): Microtubules; Primary cilium
Pathways (Reactome):
Cell Cycle: AURKA Activation by TPX2; EML4 and NUDC in mitotic spindle formation; Loss of Nlp from mitotic centrosomes; Loss of proteins required for interphase microtubule organization from the centrosome; Mitotic Prometaphase; Recruitment of NuMA to mitotic centrosomes; Recruitment of mitotic centrosome proteins and complexes; Regulation of PLK1 Activity at G2/M Transition; Resolution of Sister Chromatid Cohesion; Sealing of the nuclear envelope (NE) by ESCRT-III; Separation of Sister Chromatids; The role of GTSE1 in G2/M progression after G2 checkpoint
Vesicle-mediated transport: COPI-dependent Golgi-to-ER retrograde traffic; COPI-independent Golgi-to-ER retrograde traffic; COPI-mediated anterograde transport; Gap junction assembly; Microtubule-dependent trafficking of connexons from Golgi to the plasma membrane; Translocation of SLC2A4 (GLUT4) to the plasma membrane
Metabolism of proteins: Carboxyterminal post-translational modifications of tubulin; Formation of tubulin folding intermediates by CCT/TriC; Post-chaperonin tubulin folding pathway; Prefoldin mediated transfer of substrate to CCT/TriC
Organelle biogenesis and maintenance: Anchoring of the basal body to the plasma membrane; Cargo trafficking to the periciliary membrane; Intraflagellar transport
Signal Transduction: Hedgehog 'off' state; RHO GTPases Activate Formins; RHO GTPases activate IQGAPs
Immune System: MHC class II antigen presentation; PKR-mediated signaling
Neuronal System: Activation of AMPK downstream of NMDARs; Assembly and cell surface presentation of NMDA receptors
Autophagy: Aggrephagy
Cellular responses to stimuli: HSP90 chaperone cycle for steroid hormone receptors (SHR) in the presence of ligand
Developmental Biology: Recycling pathway of L1
Disease: HCMV Early Events
Hemostasis: Kinesins
Gene Ontology:
Molecular function: identical protein binding; protein binding; GTP binding; GTPase activity; structural constituent of cytoskeleton; structural molecule activity; microtubule binding; protein heterodimerization activity; protein-containing complex binding; protein-folding chaperone binding
Biological process: cell division; cytoskeleton-dependent intracellular transport; microtubule-based process; mitotic cell cycle; neuron differentiation; 'de novo' protein folding; adult behavior; adult locomotory behavior; cellular response to calcium ion; centrosome cycle; cerebellar cortex morphogenesis; cerebral cortex development; dentate gyrus development; flagellated sperm motility; forebrain morphogenesis; gene expression; glial cell differentiation; hippocampus development; homeostasis of number of cells within a tissue; intracellular protein transport; locomotory behavior; locomotory exploration behavior; memory; microtubule cytoskeleton organization; microtubule polymerization; and 17 more
Cellular component: axonemal microtubule; cilium; cytoplasmic ribonucleoprotein granule; extracellular exosome; microtubule; microtubule cytoskeleton; nucleus; recycling endosome; cytosol; condensed chromosome; cytoplasmic microtubule; cytoskeleton; microtubule plus-end; neuromuscular junction; plasma membrane; sperm flagellum; synapse
Genetic constraint (gnomAD): Loss-of-function variants: 7 observed, 35.53 expected, observed/expected ratio (o/e) 0.2, 90% interval 0.11 to 0.37. The upper end of that interval is the gene's LOEUF score, 0.37, which puts it in group 1 of 6, group 1 being the genes least tolerant of losing a copy. Missense variants: 19 observed, 611.85 expected, observed/expected ratio (o/e) 0.0311, 90% interval 0.021 to 0.046. Synonymous variants: 193 observed, 214.58 expected, observed/expected ratio (o/e) 0.9, 90% interval 0.8 to 1.01.
Gene-disease validity (ClinGen):
ClinGen rates the evidence that TUBA1A causes each of these diseases.
tubulinopathy (autosomal dominant): Definitive. A nervous system disorder characterized by complex cortical malformations including in most cases dysmorphic basal ganglia and/or corpus callosum in which the cause of the disease is a variation in a tubulin gene.
Homologues: Orthologues: chimpanzee TUBA1A (100% identical), mouse Tuba1a (100% identical), macaque TUBA1A (99% identical), pig TUBA1A (99% identical), Drosophila melanogaster alphaTub84B (97% identical), Drosophila melanogaster alphaTub84D (96% identical). Paralogues in human: TUBA1B (99% identical), TUBA1C (98% identical), TUBA3C (98% identical), TUBA3D (98% identical), TUBA3E (96% identical), TUBA4A (96% identical), TUBA8 (90% identical), TUBAL3 (73% identical), TUBB4B (43% identical), TUBB4A (43% identical), TUBB3 (43% identical), TUBB (42% identical), and 11 more.
Diseases named in the same sentence as TUBA1A in open-access papers:
TUBA1A is named in the same sentence as 94 diseases in open-access papers, as found by Europe PMC text mining. Sharing a sentence is not in itself a finding about the gene and the disease. The quoted sentences say what the papers report.
Lissencephaly (44 papers, 2007 to 2026). A spectrum of malformations of cortical development caused by insufficient neuronal migration that subsumes the terms agyria, pachygyria and subcortical band heterotopia. "Neonatal mutations in TUBA1A are associated with severe brain malformations, and approximately 70% of patients with reported cases of TUBA1A mutations exhibit lissencephaly." (PMID 38813542, 2024). "TUBA1A mutations are associated with severe congenital lissencephaly, due to abnormal neuronal migration involving neocortical and hippocampal lamination, corpus callosum, cerebellum, and brainstem." (PMID 38459225, 2024). "We realized that the NIH ClinVar database describes a case of lissencephaly (864867) associated with a K394N substitution to TUBA1A and MS data verifies that K394 is acetylated in human TUBA1A." (PMID 38064432, 2023). "We also examined the impact of the p.R402H substitution, which has been previously associated to severe lissencephaly, on TUBA1A stability and microtubule incorporation." (PMID 37435044, 2023). "Two pathogenic variants in TUBA1A have been reported at this residue, V409I and V409A, identified in individuals with pachygyria and agyria (mild and severe lissencephaly) respectively." (PMID 36875768, 2023). "A fetus with lissencephaly carried a heterozygous novel missense variant in TUBA1A (NM_006009.3: c.680T>A, p.(Leu227Gln); SCV001519080)." (PMID 34974531, 2022). "The child that received 31 examinations was an outlier: a 3.5 year old child with TUBA1A mutations causing lissencephaly and infantile spasms managed on vigabatrin from 2009 to 2021, with examinations every 3–6 months over that period." (PMID 35817277, 2022). "Here, we focus on two mutations at the valine 409 residue of TUBA1A, V409I, and V409A, identified in patients with pachygyria or lissencephaly, respectively." (PMID 35511030, 2022). "A recurrent mutation (R402H) in the α-tubulin gene TUBA1A is known to cause lissencephaly with cerebellar and striatal phenotypes." (PMID 33137126, 2020). "In this study we investigate how a common mutation (R402H) in TUBA1A causes lissencephaly by generating and characterising a mouse with the same variant." (PMID 33137126, 2020). "In this study we have investigated the pathology and molecular mechanisms that result from an R402H mutation in TUBA1A, a variant that is known to cause lissencephaly in the human population." (PMID 33137126, 2020). "One mutation of particular interest is the R402H variant in TUBA1A, which has been reported in multiple unrelated patients with lissencephaly, whom also present with cerebellar hypoplasia and striatal abnormalities." (PMID 33137126, 2020). "This has been observed in the case of the recurrent c.1205G>A, p.(Arg402His) variant in TUBA1A causing classic lissencephaly, and the c.790C>T, p.(Arg264Cys) variant in the same gene associated with central pachygyria." (PMID 29706637, 2018). "Few TUBA1A mutations that lead to lissencephaly have been satisfactorily linked to the migratory pathway." (PMID 29057214, 2017). "Contrary to lissencephaly, where cortical migration provides a clear culprit for the malformation, the complex etiology of polymicrogyria makes it difficult to predict how TUBA1A mutations contribute to the molecular basis of the disease." (PMID 29057214, 2017). "TUBA1A mutations lead to a variety of brain malformations ranging from lissencephaly with perisylvian pachygyria to diffuse posteriorly predominant pachygyria, combined with internal capsule dysgenesis, cerebellar dysplasia, and callosal hypotrophy." (PMID 29109381, 2017). "Patients containing TUBA1A mutations exhibit a wide variety of cerebral cortex malformation phenotypes including lissencephaly, pachygyria, microlissencephaly, and polymicrogyria." (PMID 29057214, 2017). "Patients with mutations in TUBA1A present 5 classes of brain malformations including microlissencephaly, lissencephaly, and polymicrogyria, and a broad spectrum of clinical effects." (PMID 29057214, 2017).
Lissencephaly (continued). "Polymicrogyria-causing TUBA1A mutations are significantly less common than lissencephaly-causing mutations (~13%), suggesting that perhaps only very specific disruptions of tubulin function can lead to polymicrogyria." (PMID 29057214, 2017). "In fact, “lissencephaly with cerebellar hypoplasia” is a common class of TUBA1A mutation-induced phenotype." (PMID 29057214, 2017). "In fact, lissencephaly is the most prominent malformation attributed to TUBA1A mutations, with over 90% of patients exhibiting some form of lissencephaly malformation." (PMID 29057214, 2017). "We established iPSCs derived from two TUBA1A-associated lissencephaly patients and successfully modeled one aspect of the pathogenesis of lissencephaly in vitro using iPSC-NPCs and iPSC-derived neurons." (PMID 27431206, 2016). "TUBA1A mutation-associated lissencephaly is characterized by cerebellar hypoplasia and often involves the hypoplasia of the brain stem, including the midbrain and pons." (PMID 27431206, 2016). "Further investigation into TUBA1A regulation is needed to understand the detailed mechanism of TUBA1A-associated lissencephaly." (PMID 27431206, 2016). "In humans, TUBA1A mutations have been identified in lissencephaly patients whose brains showed a smooth surface owing to severely impaired lamination of the cerebral cortex." (PMID 27431206, 2016). "TUBA1A mutations are identified in 1 % of classic lissencephaly and 30% of lissencephaly with cerebellar hypoplasia." (PMID 26541977, 2015). "Mutations of TUBA1A, which encodes alpha tubulin, cause lissencephaly spectrum, particularly diffuse agyria or perisylvian pachygyria, with microcephaly, agenesis of the corpus callosum, and cerebellar hypoplasia." (PMID 26052266, 2015). "The constructs were for wild-type, p.R64W, and p.C25F, as well as p.R402C, which is a recurrent TUBA1A mutation that expresses the phenotype of classical lissencephaly, similar to LIS1 mutations." (PMID 26493046, 2015). "TUBA1A mutations account for only 1% of isolated classical lissencephaly; however, they account for approximately 30% of patients with lissencephaly associated with cerebellar hypoplasia." (PMID 26052266, 2015). "Another lissencephaly-associated protein, tubulin alpha 1A (Tuba1a), is also involved in hippocampal layer formation." (PMID 25964735, 2015). "The majority of patients with classical lissencephaly (4/7) or with LCH (3/7) also carried mutations in TUBA1A gene (6/7)." (PMID 25059107, 2014). "All foetuses with lissencephaly and cerebellar hypoplasia carried distinct TUBA1A mutations, while those with classical lissencephaly harbored recurrent mutations in TUBA1A (3 cases) or TUBB2B (1 case)." (PMID 25059107, 2014). "The additional major finding is that TUBA1A mutations are responsible for a wide spectrum of foetal brain malformations ranging from the most severe; microlissensencephaly to classical lissencephaly, and in some cases to polymicrogyria." (PMID 25059107, 2014). "Given the involvement of mutations in TUBA1A in phenotypes with lissencephaly and other similar clinical findings to the severe XLAG phenotype due to mutations in ARX we wanted to investigate the novel interaction between ARX and TUBA1A further." (PMID 20148114, 2010). "Both the human lissencephaly R402H TUBA1A mutation and tba-1(ju89) G414R mutations are predicted to alter the H11–H12 loop of alpha-tubulin." (PMID 20300184, 2010). "Heterozygous mutations in TUBA1A gene, which encodes for one of the major neuronal α-tubulins, has been associated, so far, with severe brain malformations including lissencephaly, cerebellar hypoplasia, agenesis of the corpus callosum, and brain stem anomalies." (PMID 37435044, 2023). "We could show that particular malformations of cortical (lissencephaly, agyria) and extracortical (complete agenesis of the CC, brainstem hypoplasia) brain structures were associated with epilepsy in TUBA1A and TUBB2B tubulinopathies, respectively." (PMID 33082561, 2021).
Lissencephaly (continued). "Furthermore, sporadic cases with posterior-biased subcortical band heterotopia and lissencephaly were associated with mutations in genes either encoding the platelet-activating factor acetylhydrolase (PAFAH1B1) or tubulin alpha-1A (TUBA1A)." (PMID 34211111, 2021). "Human TUBA1A tubulinopathy patients with heterozygous mutations in TUBA1A exhibit severe brain malformations including defects in commissure formation and changes to cortical folding patterns (lissencephaly, polymicrogyria, pachygyria)." (PMID 35127710, 2021). "Based on available information, major neuroradiological features of TUBA1A-associated tubulinopathy include anomalies of the cortical gyration (99.0%, 95/96), with lissencephaly [agyria-pachygyria (HP:0031882, HP:0001302)] and polymicrogyria reported in 70.0% (67/96) and 18.8% (18/96) respectively." (PMID 30744660, 2019). "The severity of cerebellar abnormality in lissencephaly ranges from discrete midline hypoplasia to disturbed foliation and volume reduction, later being most commonly associated with the involvement the TUBA1A and RELN genes." (PMID 31355197, 2019). "This case shows that TUBA1A mutations lead to a variety of brain malformations ranging from lissencephaly with perisylvian pachygyria to diffuse posteriorly predominant pachygyria, combined with internal capsule dysgenesis, cerebellar dysplasia, and callosal hypotrophy." (PMID 29109381, 2017). "In our simple assay, randomly oriented neurons migrated from the neurospheres generated from the iPSCs with the p.N392S TUBA1A mutation, which might partially reflect the in vivo pathology of the patients with TUBA1A mutation-associated lissencephaly." (PMID 27431206, 2016). "Regional phenotypic differences in TUBA1A mutation-associated lissencephaly also might be partially explained by differences in the transcriptional regulation of TUBA1A throughout the brain." (PMID 27431206, 2016). "To overcome these limitations, we generated induced pluripotent stem cells (iPSCs) from the umbilical cord and peripheral blood of two lissencephaly patients with different clinical severities carrying alpha tubulin (TUBA1A) missense mutations (Patient A, p.N329S; Patient B, p.R264C)." (PMID 27431206, 2016). "Our data suggest that the TUBA1A mutations disrupting lateral interactions have pronounced dominant-negative effects on microtubule dynamics that are associated with the severe end of the lissencephaly spectrum." (PMID 26493046, 2015). "TUBA1A mutations cause a wide spectrum of lissencephaly and brain malformations." (PMID 26493046, 2015). "Mutations in human and mouse alpha-tubulin, TUBA1A (TUB3A) cause lissencephaly." (PMID 20300184, 2010). "Histological examinations in TUBA1A mutated brains revealed structural abnormalities of the cortex, a fractured pyramidal layer of the hippocampus, and defects attributed to impairment of neuronal migration mechanisms, similar to the mouse models of lissencephaly (LIS1, DCX, RELN)." (PMID 31269740, 2019). "For the TUBA1A gene, case reports have described that although cortical malformation resembling classical lissencephaly could be detected in all patients with mutations of this gene, specific combinations of features could be identified depending on the particular genetic alteration that is present." (PMID 29109381, 2017). "However, inferences can be made about the functions of TUBA1A that may be important for migration based on how MAPs interact with microtubules and on the limited molecular data available on some of the lissencephaly patient TUBA1A mutations." (PMID 29057214, 2017). "In our present study, we identified two novel heterozygous missense TUBA1A mutations in patients with severe cortical dysgeneses, one with an extremely thin cerebral parenchyma apparently looking like hydranencephaly and the other with lissencephaly accompanied by marked hydrocephalus." (PMID 26493046, 2015).